MALAT1 (metastasis associated lung adenocarcinoma transcript 1)
Diseases named in the same sentence as MALAT1 in open-access papers (continued):
Sharing a sentence is not in itself a finding about the gene and the disease.
multiple myeloma (continued). "Of note, the expression of MALAT1 in newly diagnosed patients was not correlated with the percentage of plasma cells in the bone marrow suggesting that interaction between myeloma cells and bone marrow microenvironment may influence MALAT1 expression." (PMID 27177333, 2016). "Further analysis by fluorescent in-situ hybridization with larger cohort may provide more impactful insight on the clinical relevance of MALAT1 expression in multiple myeloma." (PMID 25369863, 2014). "In conclusion, this study revealed that MALAT1 was overexpressed in patients with multiple myeloma, and this lncRNA may play a role in the pathogenesis of the disease." (PMID 25369863, 2014). "Therefore, the aim of the present study was to evaluate the expression of MALAT1 in bone marrow mononuclear cells from patients with multiple myeloma and with different disease status and healthy individuals." (PMID 25369863, 2014). "Additionally, lncRNA MALAT1 is upregulated in multiple myeloma serums and cells." (PMID 33652661, 2021). "MALAT1 was overexpressed in patients with myeloma and may play a role in its pathogenesis." (PMID 25369863, 2014). "This suggests that MALAT1 may be deregulated and overexpressed in patients with multiple myeloma." (PMID 25369863, 2014). "However, we hypothesized the magnitude of the change (decrease) after myeloma-related therapy may have been related to the degree of treatment response and prognosis, because the expression of MALAT1 changed after treatment." (PMID 25369863, 2014). "Taken together, we hypothesized that MALAT1 may play a role in multiple myeloma." (PMID 25369863, 2014). "In multiple myeloma xenografts, MALAT1 LNA-gapmeR or nanotube-delivered anti-MALAT1 oligos trigger apoptosis and impair tumor growth, demonstrating nuclear target engagement and therapeutic effect in vivo." (PMID 41191214, 2025). "This analysis resulted in the identification of four distinct cell subsets: C0 IGLL5+ Myeloma Cells, C1 IGHG4+ Myeloma Cells, C2 MALAT1+ Myeloma Cells, and C3 IGHG1+ Myeloma Cells." (PMID 39281682, 2024). "In a meta-analysis which encompassed 15 types of cancers including diffuse large B-cell lymphoma (DLBCL), multiple myeloma (MM), and CLL, high MALAT1 expression was found to be a good prognostic factor for OS in B-cell neoplasms." (PMID 38255996, 2024). "Many lncRNAs, such as MALAT1, GAS5, DLEU2, and H19, have been reported to be involved in the diagnosis and progression of multiple myeloma (MM)." (PMID 36607351, 2023). "For example, a recent study revealed that targeting the MALAT1/PARP1 (poly ADP-ribose polymerase 1) / LIG3 (DNA Ligase 3) complex resulted in DNA damage and apoptosis in multiple myeloma." (PMID 36829256, 2023). "The evaluation of lncRNAs expression in plasma samples from leukemia and multiple myeloma showed that TUG1, MALAT1, HOTAIR and GAS5 are more highly expressed in leukemia than in the control samples, and only lincRNA-p21 is upregulated in multiple myeloma." (PMID 25338714, 2015). "Moreover, lncRNA MALAT1 was also found to interact with PARP1, influencing the DNA damage and apoptosis in multiple myeloma cells." (PMID 36597139, 2023). "MALAT1 in another hematological cancer, multiple myeloma (MM) has been shown to also target latent transforming growth factor beta-binding protein 3 (LTB3) and suggest that MALAT1 may have widespread effects across different transcription complexes." (PMID 27998273, 2016). "Although most of these stage-specific lncRNAs have not been functionally characterized, hub lncRNA MALAT1 is well known to promote cancer metastasis in lung, colorectal, bladder and multiple myeloma when its expression was up-regulated." (PMID 26863568, 2016). "Isin and colleagues reported that several circulating LncRNAs including TUG1, LincRNA-p21, MALAT1, HOTAIR, and GAS5 could be the potential biomarkers for diagnosis of chronic lymphocytic leukemia (CLL) and multiple myeloma (MM)." (PMID 26221732, 2015).
multiple myeloma (continued). "Our study analyzed the expression of MALAT1 in bone marrow mononuclear cells rather than plasma samples, because the pathogenesis of myeloma is closely related to bone marrow." (PMID 25369863, 2014). "Second, we didn’t evaluate the expression of MALAT1 in patients resistant to myeloma therapy due to no available samples." (PMID 25369863, 2014). "Additionally, the most activated TFs in each subgroup within the M1-M5 modules were identified as follows: MAF in the C0 IGLL5+ Myeloma Cells subgroup, LEF1 in the C1 IGHG4+ Myeloma Cells subgroup, TCF12 in the C2 MALAT1+ Myeloma Cells subgroup, and CREB5 in the C3 IGHG1+ Myeloma Cells subgroup." (PMID 39281682, 2024). "We observed that the patients with a greater decrease in MALAT1 after initial treatment had a significantly prolonged PFS, which is consistent with the current consensus that therapeutic intervention to achieve a maximal response is beneficial for patients with multiple myeloma." (PMID 25369863, 2014).
renal cell carcinoma (52 papers, 2014 to 2025). "Some researchers havereported a high frequency of mutations in the MALAT1 locus(e.g., translocation in MALAT1 in renal cell carcinoma andgastroblastoma cells is established)." (PMID 37538803, 2023). "For example, overexpression of lncRNA MALAT1 (metastasis-associated lung adenocarcinoma transcript 1) promotes aggressive phenotypes of renal cell carcinoma by regulating cell proliferation and invasion." (PMID 31142627, 2019). "For example, increased expression of the lncRNA metastasis-associated lung adenocarcinoma transcript 1 (MALAT1) in renal cell carcinoma was reported to promote aggressive biological behavior through interactions with EZH2." (PMID 28412742, 2017). "In renal cell carcinoma, sunitinib resistance is showed to be positive associated with dramatical up‐regulation of MALAT1, and the chemoresistance could be reversed by MALAT1 knock‐down." (PMID 34164906, 2021). "MALAT1 is frequently overexpressed in renal cell carcinoma (RCC) cell lines and primary tumor samples as compared to normal tissues; moreover, high MALAT1 expression associated with worse overall survival in RCC patients." (PMID 29739426, 2018). "A study meta-analyzed the associations between lncRNA-MALAT1 expression and clinicopatholoical characteristics corroborates our findings: MALAT1 level was demonstrated to be closely associated with clinical stage and lymph node metastasis in renal cell carcinoma." (PMID 28415638, 2017). "A chromosomal translocation involving breakpoints at 11q13.1 leads to the fusion of MALAT1 with different genes or noncoding regions, such as Alpha‐TFEB, and activation of MALAT1 in renal cell cancer." (PMID 40783798, 2025). "Luciferase reporter assays confirmed a targeted relationship between MALAT1 and miR-203a-3p, and expression level analyzes showed significant upregulation of miR-203a-3p in si-MALAT1 transfected renal cell carcinoma lines." (PMID 35922756, 2022). "MALAT1 is over-expressed in human mantle cell lymphoma and renal cell carcinoma tissues, compared with normal counterparts, and high levels of MALAT1 are associated with advanced disease stage and reduced patient survival." (PMID 32174966, 2020). "Another study has demonstrated that MALAT1 interacts with EZH2 and that the oncogenesis induced by lncRNA MALAT1 can be inhibited by EZH2 depletion in renal cell carcinoma." (PMID 31830649, 2020). "In renal cell carcinoma, MALAT1 promoted tumor cell proliferation and invasion by interacting with EZH2 and miR-205." (PMID 32393270, 2020). "In conclusion, MALAT1 accelerates the development and progression of renal cell carcinoma by decreasing the expression of miR‐203 and promoting the expression of BIRC5." (PMID 31250518, 2019). "As one of the first found lncRNAs which were associated with cancers, MALAT1 was extensively expressed in human tissues, and the role of MALAT1 in human diseases such as nasopharyngeal carcinoma and aggressive renal cell carcinoma has been confirmed." (PMID 31343412, 2019). "MALAT1 in renal cell carcinoma (RCC) and CASC15 in GC induce EMT by decreasing the level of E-cadherin." (PMID 31575017, 2019). "Silencing of MALAT1 expression reduced cell proliferation and invasion and increased apoptosis in renal cell carcinoma cells." (PMID 28412742, 2017). "MALAT-1 induced the high expression of the Livin protein which leads to proliferation and metastasis of renal cell carcinoma." (PMID 28039476, 2017). "It has been shown that Malat1 promotes aggressive Renal Cell Carcinoma by regulating EZH2 as a ceRNA for miR-205." (PMID 27191262, 2016). "Other studies confirmed that MALAT1 sponges miR-203a-3p in renal cell carcinoma." (PMID 35922756, 2022). "Aggressive renal cell carcinoma was promoted by lncRNA MALAT1 via regulation of Ezh2." (PMID 34335862, 2021). "In addition, in renal cell carcinoma, MALAT1 can regulate the miR‐203/BIRC5 axis to accelerate tumor progression." (PMID 34240756, 2021).
renal cell carcinoma (continued). "MALAT1 is also involved in promoting renal cell carcinoma through interaction with miRNA-205-5p." (PMID 32993558, 2020). "For example, overexpression of lncRNA MALAT1 confers an oncogenic function in renal cell carcinoma." (PMID 31830649, 2020). "For example, mechanistic investigations showed that lncRNA MALAT1 in renal cell carcinoma was over-expressed and MALAT1 could emerge as a new gene regulator or prognostic marker." (PMID 32117916, 2020). "MALAT1 is transcriptionally activated by c-Fos in renal cell carcinoma cells." (PMID 32174966, 2020). "Moreover, MALAT1 is highly expressed in human renal cell carcinoma tissues, and MALAT1 silencing resulted in decreased cell proliferation and invasion and increased apoptosis." (PMID 31619581, 2019). "We aimed to investigate the roles of the lncRNA MALAT1 in renal cell carcinoma (RCC) progression." (PMID 31250518, 2019). "MALAT1 interacts with EZH2 to suppress E-cadherin (CDH1) expression in renal cell carcinoma." (PMID 26871474, 2016). "Overexpression of MALAT1 confers an oncogenic function in renal cell carcinoma (RCC) that may offer a novel theranostic marker in this disease." (PMID 27782152, 2016). "Recent studies have also reported that lncRNA metastasis-associated lung adenocarcinoma transcript 1 (MALAT1) could promote epithelial-to-mesenchymal transition (EMT) and metastasis in many cancers, including renal cell carcinoma, oral squamous cell carcinoma, and endometrioid endometrial carcinoma." (PMID 29416735, 2018). "The two most significant GO BP terms for MALAT1 (Metastasis associated lung adenocarcinoma transcript 1) were ion transport (GO:0006811) and excretion (GO:0007588), which seems to be consistent with the observation that MALAT1 often is associated with kidney function and with renal cell carcinoma." (PMID 30567492, 2018). "However, in renal cell carcinoma, high expression of MALAT-1 and the Livin protein were identified." (PMID 28039476, 2017). "MALAT1 has also been reported in EVs derived from CRC cells, renal cell carcinoma (RCC) cells, and the sera from patients with pancreatic ductal adenocarcinoma." (PMID 36835116, 2023). "MALAT1 reduces the expression of miR-203 to promote the expression of BIRC5 and accelerate the occurrence and development of renal cell carcinoma." (PMID 34193046, 2021). "MALAT1 has been identified as a negative prognostic marker in many types of cancers (e.g., gastric cancer, colorectal cancer, renal cell carcinoma, and hepatocellular carcinoma after liver transplantation)." (PMID 35954272, 2022). "MALAT-1 was also demonstrated to induce EMT in squamous cell carcinoma of the tongue via the Wnt/β-catenin signalling pathway, while MALAT-1 knockdown in renal cell carcinoma decreased expression of β-catenin and transcription factor c-Myc, a downstream effector of Wnt/β-Catenin signalling." (PMID 28430163, 2017).
colon carcinoma (50 papers, 2013 to 2025). "lncRNAs are also involved in the chemokine regulation of colon tumors; for example, chemokine ligand 5 is engaged in tumor-associated dendritic cell-mediated colon cancer progression through noncoding RNA MALAT-1." (PMID 36393968, 2022). "MALAT1 was also associated with colon cancer progression by stimulating tumor associated dendritic cells (TADC)-derived production of CCL5; consistently, MALAT1 blockade by siRNAs significantly dampened CCL5-induced migration and invasion of CRC cells." (PMID 29739426, 2018). "For example, the association between colon cancer and MALAT1, HOTAIR, UCA1, KCNQ10T1, and CRNDE (ranked 2nd, 4th, 6th, 7th, 9th in the prediction results, respectively) were validated by lncRNADisease database or MNDR database." (PMID 26577439, 2015). "In addition, metastasis associated lung adenocarcinoma transcript 1 (MALAT1) is highly expressed in several colon cancer cell lines such as LoVo, HCT116, SW480, and HT29 compared with normal intestinal epithelial HIEC cells." (PMID 33246471, 2020). "The up-regulation of the lncRNA metastasis associated lung adenocarcinoma transcript 1 (MALAT1) mediates high mobility group box 1 (HMGB1) expression in colon cancer via competing with miR-129-5p, and the MALAT1/miR-129-5p/HMGB1 axis serves as a key prognostic marker in the development of the tumor." (PMID 32117736, 2020). "Resveratrol decreases colon cancer resistance by downregulating MALAT1 and mediating the Wnt/β-catenin signaling pathway." (PMID 40352931, 2025). "While MALAT1's involvement in multiple kinds of cancer, such as prostate and colon cancer, is well-documented, its roles and mechanisms can vary in different contexts." (PMID 39323624, 2024). "MALAT-1 expression in colon cancer tissues, its impact on SW480 cells' proliferation and apoptosis, and the signaling route underlying these effects were all examined by Zhang and colleagues." (PMID 38511067, 2024). "Malat1 proved useful in finding a more effective treatment for colon cancer as autophagy activation by miR-101 expression inhibition in cancer cell lines promotes cell proliferation and reduces apoptosis." (PMID 37340009, 2023). "The metastasis-associated lung adenocarcinoma transcript 1 (MALAT1) rs664589G allele was associated with gene upregulation and accelerated colon cancer growth/metastasis." (PMID 35454158, 2022). "MALAT1 has also been found to be overexpressed in human colon cancer cell lines including LoVo, SW620, SW1116, HCT116, SW480, HT29, and COLO205 cells compared to the normal human intestinal epithelial cells." (PMID 35922756, 2022). "MALAT1 was reported to be highly expressed in colon cancer and to contribute to tumor progression 42-44." (PMID 34671200, 2021). "Metastasis-associated lung adenocarcinoma transcript 1(MALAT1) in exosomes increased FUT4-mediated fucosylation and phosphorylation of the PI3K/Akt/mTOR pathway and promoted invasion and metastasis in colon cancer cells." (PMID 34948129, 2021). "We investigated MALAT1 expression in colon cancer tissues, the effect of MALAT1 on proliferation and apoptosis of SW480 cells, and the signaling pathway involved in the MALAT1 effects." (PMID 31733641, 2020). "MALAT1 expression was determined in 60 colon cancer and para-carcinoma tissues using reverse transcription polymerase chain reaction (RT-PCR)." (PMID 31733641, 2020). "The results of our study suggest that MALAT1 acts as an endogenous inhibitor of Wnt/β-catenin in colon cancer cells, affecting cell proliferation and apoptosis." (PMID 31733641, 2020). "In this study, we investigated MALAT1 expression in colon cancer tissues, the effect of MALAT1 on proliferation and apoptosis of SW480 cells, and the signaling pathway involved in the MALAT1 effects." (PMID 31733641, 2020).
colon carcinoma (continued). "MALAT1 is also increased in colon cancer cells, directly binding to miR-663a, thus acting as a competing endogenous lncRNA; as a result, important cancer-related miR-663a targets (TGFB1, PIK3CD, P21, JunB, and JunD) were affected." (PMID 32183400, 2020). "Other studies showed that an increased MALAT1 expression promotes the proliferation of colon cancer cells, although by regulating other targets such as SOX9 and miR-129-5p/HMGB1 axis." (PMID 31733641, 2020). "The RT-PCR analysis showed that MALAT1 expression in colon cancer tissues was significantly higher (i.e. more than 5 times) than in para-carcinoma tissues (p < 0.05)." (PMID 31733641, 2020). "Despite these limitations, our study revealed that MALAT1 exerts an important regulatory effect on colon cancer cells." (PMID 31733641, 2020). "MALAT1 knockout had an inhibitory effect on the proliferation of colon cancer cells, with a statistically significant difference compared to untreated control group at 24 h, 48 h, and 72 h (p < 0.05)." (PMID 31733641, 2020). "It is obvious that the apoptosis rate was the highest in MALAT1 siRNA group, confirming the promoting effect of MALAT1 knockout on apoptosis in colon cancer cells." (PMID 31733641, 2020). "Inhibition of MALAT1 can promote the apoptosis and hinder the proliferation of colon cancer cells by restraining the activation of the Wnt/β-catenin signaling pathway, ultimately exerting antitumor effects." (PMID 31733641, 2020). "From our literature review, we found that several lncRNAs among the ceRNA network, such as lncRNAs UCA1, GAS5, MALAT1, and PVT1, are associated with oncogenesis and the development of colon cancer." (PMID 30984308, 2019). "In this study, it was found that in colon cancer (CC) cells, MALAT1 and miR663a were reciprocally repressed in cDNA array screening and qRT-PCR analysis." (PMID 30154407, 2018). "As a result, the associations between colon cancer and HOTAIR, CRNDE, and MALAT1 (top 3 predictions) were verified by the updates in the LncRNADisease database." (PMID 28963512, 2017). "In colon cancer cell lines, overexpression of MALAT-1 promotesproliferation, migration and invasion." (PMID 27508057, 2016). "The expression level of MALAT1 is increased in resistant colon cancer cells." (PMID 40352931, 2025). "They discovered that the expression of MALAT-1 was much more significant in colon cancer tissues when compared with para-carcinoma tissues, indicating that it might be involved in the emergence of colon cancer." (PMID 38511067, 2024). "Studies have shown that MALAT1 may play a similar role in colon cancer cells by inhibiting Wnt/β-catenin signaling." (PMID 37235843, 2023). "For instance, the lncRNA MALAT1, which is upregulated in colon carcinoma, may accelerate colon cancer cell growth." (PMID 35992788, 2022). "Also in the derived HT-29FUR subline of 5FU-resistant cells, the level of MALAT1 was more than 2 times higher compared to the parent colon cancer HT-29 cell line." (PMID 35922756, 2022). "Interestingly, a substantially cytosolic localization of MALAT1 has been demonstrated in three colon cancer lines (HCT116, SW480, SW620), although this result will need to be confirmed in other cell lines and in CRC samples." (PMID 35922756, 2022). "Considering the important role of the Wnt/β-catenin pathway in the occurrence and development of colon cancer we investigated whether the activation of the Wnt/β-catenin pathway in colon cancer is regulated by MALAT1." (PMID 31733641, 2020). "The number of apoptotic cancer cells in MALAT1 siRNA group was about 15 times higher than in untreated control group (p < 0.05), suggesting again the pro-apoptotic effect of MALAT1 knockout on colon cancer cells." (PMID 31733641, 2020). "MALAT1 is expected to be a new target in the treatment of colon cancer in the future." (PMID 31733641, 2020).